ENSG00000276048
Gene: Miscellaneous RNA gene on chromosome 2 (44,937,426 to 44,937,696, forward strand). Ensembl gene ENSG00000276048.
Gene Ontology:
Biological process: regulation of gene expression